IL1B (interleukin 1 beta)
Diseases named in the same sentence as IL1B in open-access papers (continued):
Sharing a sentence is not in itself a finding about the gene and the disease.
cancer (continued). "Here, we show that KRAS-mutant cancers display specific non-oncogene addiction to host-provided IL-1β in humans and mice." (PMID 36980752, 2023). "Key events in this process are mediated by IL-1β and IL-18 signaling, as both cytokines accelerate the expression of vascular cell adhesion molecule 1 (VCAM1) in hepatic sinusoidal endothelial cells (HSECs), assisting the adhesion of cancer cells." (PMID 37891577, 2023). "Daily consumption of dark tea can achieve cancer prevention by inhibiting pro-inflammatory cytokines TNF-α, IL-1β, and IL-6 and increasing anti-inflammatory cytokines IL-10 and IL-22, which is mainly attributed to the down-regulation of the NF-κB signaling pathway." (PMID 37764687, 2023). "CXCL8, IL1β and PTGS2 are inflammatory mediators that may play an important role in cancer progression by regulating CSC proliferation and self-renewal." (PMID 37138170, 2023). "Furthermore, taxanes, including paclitaxel, induced an increase in IL-1β, IL-6, and TNF-α levels in patients with cancer." (PMID 37275575, 2023). "Importantly, we show that targeting IL-1β and/or versican can be an effective treatment for KRAS-mutant cancers, holding great promise for cancer patients." (PMID 36980752, 2023). "Furthermore, chronic gastric inflammation is an important factor in promoting GIM and cancer progression, and IL-6, TNF-α, and IL-1β are characteristic cytokines involved in the inflammatory response." (PMID 38096029, 2023). "Next, to identify the responsible factors activating NF-κB, we have treated cells (EP and LP) with MDSC supernatant in presence/absence of IL-6, IL-10 and IL-1β neutralizing antibodies, keeping untreated cancer cells as a control." (PMID 38304256, 2023). "STAT signaling is one of the most well-characterized mode of PD-L1 induction in cancer cells, but IL-1β primarily signals though NFκB pathway, therefore, we were surprised to see an increase in p-STAT1 and p-STAT3 levels in HCC827 cells treated with IL-1β." (PMID 37985999, 2023). "The identified up-regulated genes with H3K27Ac engagement included the inflammatory response genes IL1α, IL1β, and SERPINB2; the HBEGF gene that mediates cell migration and invasion; PLAU, which is regulated by AP-1 and drives cancer metastasis; and LAMC2, which is involved in the EMT process." (PMID 37511268, 2023). "These proinflammatory cytokines are generally responsible for immune response activation (i.e., IL-6), cytotoxic and cytostatic effects against cancer cells (i.e., TNF-α), and the recruitment and activation of immune cells along with other pro-inflammatory cytokines (i.e., IL-1β)." (PMID 37760610, 2023). "Furthermore, H. pylori infection is also known to stimulate the production of proinflammatory cytokines such as IL-1β, TNF-α, and IL-6, thus creating a microenvironment that promotes cancer cell growth and survival." (PMID 37325512, 2023). "The expression patterns of 3 key genes were different in the pseudo-trajectories of the 3 types of cells, but IL1B and ITGA5 were more similar, suggesting that CST7 and the other two work in a different mode of action in cancer." (PMID 36969161, 2023). "In addition, the secretion of IL-1β is tightly regulated by NLRP3 inflammasome and targeting the inflammasome has emerged as a new therapeutic strategy for cancer." (PMID 37020461, 2023). "Interleukin-1 beta (IL-1β) is a critical activator of chronic inflammation and is produced by various cells including activated macrophages, myeloid-derived suppressor cells (MDSC’s), dendritic cells and neutrophils, fibroblasts and cancer cells." (PMID 37543673, 2023). "Secondly, a recent study found that MDSCs-derived IL-1β was involved in CRC chemoresistance, indicating the heterogeneity and necessity of epigenetic profiling for individualized diagnosis and treatment of cancer." (PMID 37781363, 2023).
cancer (continued). "Moreover, the upregulated expression of SOD2, IL1B, PLAUR, CXCL3, and CCL20 promoting cancer cell invasion in other tumors depended on the NF-κB mechanism." (PMID 37954130, 2023). "In addition, previous preclinical and clinical findings from aggressive human upper aerodigestive tract cancer showed that cancer-related pre-inflammatory genes, such as TNF-α, and IL-1β, were significantly overexpressed during this process." (PMID 37259369, 2023). "Plasma profiles of IL-1α and IL-1β during the perioperative period exhibited high variation between patients and did not convey a discernable trend among specific cancer types." (PMID 38067195, 2023). "Therefore, it is important to distinguish between the effects of IL-1β/IL-18 and the effects of NLRP3 inflammasome in cancer biology." (PMID 37715239, 2023). "These discrepancies may reflect the different roles of IL-1β/IL-18 and NLRP3 inflammasome in different cancer types or stages." (PMID 37715239, 2023). "Herein, a significant increase in IL-1β, IL-6, and TNF-α serum levels was detected that could support the role of proinflammatory cytokines in cancer patients." (PMID 37068081, 2023). "Discovered association between high levels of miR-21-5p of macrophages and expression of proinflammatory cytokines (IL-1β and IL-22) is connected with migration and invasion through BRG1 downregulation of the Wnt/β-catenin signaling pathway and is responsible for cancer growth and invasiveness." (PMID 36555323, 2022). "Furthermore, MC are innate immune cells inherent in tissues, which can promote angiogenesis and accelerate the progression of malignant tumors by releasing different chemokines (such as TNF-α and IL-1b) and inflammatory cytokines." (PMID 36247874, 2022). "Pyroptosis-like immunogenic cell death (ICD) leads to the severe release of immunoregulatory molecules of IL-1β, IL-18, HMGB1, and ATP, and pyroptotic cancer cells were uptaken by antigen-presenting cells which suggested that pyroptosis were closely correlated to immune activity." (PMID 36281290, 2022). "Hypomethylation across cancers was observed for AIM2, CASP8, GZMA, and IL-1B." (PMID 36605187, 2022). "Inflammatory IL-1β (MyD88) and NF-κβ signaling pathways were upregulated in SED + T compared to all other groups indicating inflammatory pathways likely play a role in the cancer-mediated cardiac dysfunction." (PMID 36531941, 2022). "To this end, we compared the relationships between OM grade, oral mucosal dryness, and inflammatory mediators (Interleukin (IL)-1β, IL-6, IL-10, IL-12p70, tumor necrosis factor (TNF), prostaglandin E2, and vascular endothelial growth factor) in patients with cancer and in healthy volunteers (HV)." (PMID 35476641, 2022). "Additionally, the uterine microbiome can stimulate the production of pro-inflammatory cytokines in endometrial cells, including IL-1α, IL-1β, IL-17α, and TNF-α, which are involved in the carcinogenesis of various cancers." (PMID 35628566, 2022). "In contrast to elevated expression of COX-2 and autophagy in NPCs, cancer cells are less sensitive to CXB without IL-1β stimulation in other studies." (PMID 36457130, 2022). "Recent reports have indicated that cancer-derived exosomes from prostate and lung cancer as well as glioblastoma cell lines stimulate the production and release of IL-1β in immune and non-immune cells." (PMID 36072935, 2022). "Meanwhile, tumors upregulated autophagy levels in cancer cells through activating surrounding monocytes in concert with monocyte-derived TNF and IL1B, and monocyte-induced autophagy promoted EMT of cancer cells but also promoted tumor metastasis by activating NFKB-SNAI1 signaling pathway." (PMID 36531059, 2022). "Overexpression of YAP rescued the defect in the expression of IL-1β and GM-CSF cytokines and CD47 expression in SIRPγ-knockdown cancer cells, supporting the notion that SIRPγ acts through the Hippo/YAP pathway to regulate the expression of IL-1β, GM-CSF, and CD47." (PMID 35229723, 2022).
cancer (continued). "During the progression of the disease, cancer cells change the properties of surrounding cells, forcing them to produce growth factors and proinflammatory cytokines, such as TNF-α, IL-1β, and TGF-β, that accelerate the acquisition of a mesenchymal-like phenotype during EMT." (PMID 35884974, 2022). "Compared to HCV-infected patients with HBV infection resolution, non-HCV infected patients with or without HBV reactivation during anti-cancer/immunosuppressive therapy or bone marrow transplantation had remarkably lower baseline IL-1β levels." (PMID 36207368, 2022). "This study takes vimentin expression as an indicator for evaluating the anti-EMT potential of resveratrol, α-viniferin, ε-viniferin, and kobophenol A in TGF-β1- or IL-1β-induced A549, MCF-7, HOS, U2OS, NCI-H460 and NCI-H520 cancer cells using western blotting and immunofluorescence." (PMID 35684095, 2022). "We observed that overexpression of YAP rescued the defect in the expression of IL-1β and GM-CSF cytokines and CD47 expression in SIRPγ-knockdown cancer cells, and also reversed heightened phagocytosis of the SIRPγ-knockdown cancer cells by macrophages." (PMID 35229723, 2022). "Prostaglandin E2 (PGE2) suppresses apoptosis in multiple cell types, and it has been shown that malignant cells release IL1β, which induces PGE2 synthesis in MSCs, which is followed by the activation of β-catenin signalling and the induction of the cancer stem cell phenotype." (PMID 35954425, 2022). "As revealed by IHC staining analysis, the proteins of CYBB, IL1A, IL1B, and SLC25A5 were mainly found in cancer cells’ nucleus, cytoplasm, and membranes; brown staining indicated positive staining; and these NRG proteins were either weakly expressed or not expressed in normal tissues." (PMID 36253777, 2022). "In different types of tumors, cancer cells produce factors involved in the myelopoiesis (VEGF, GM-CSF, IL-1β, IL-6, HIF-1α, TGF-β, COX-2), as well as in the recruitment (CCL2, CCL3) and activation (TNF-α, IL-10, IL-1β, IL-6, INF-γ, COX-2, HIF-1α) of MDSCs." (PMID 35160177, 2022). "Conversely in HCV-infected patients with resolved HBV infection, non-HCV infected patients with HBV reactivation during anti-cancer/immunosuppressive therapy or BMT had significantly higher IL-1β levels than did those without HBV reactivation." (PMID 36207368, 2022). "Accordingly, the cancer cells play a key role in neutrophil infiltration into TME by producing different signals including chemokines (e.g., IL-8, CCL2, CXCL6) and cytokines (e.g., IL-1β, IL-6, TNFα)." (PMID 36330498, 2022). "Furthermore, T4 is seen modulating inflammatory genes, such as TNF-β1 and IL-1β, and downregulating COX-2, potentially altering cancer progression." (PMID 36430573, 2022). "The peptide biodistribution in liver, spleen and kidneys of IL1B mice was similar to those observed in other mouse models of cancer after intravenous injection (data not shown)." (PMID 35006394, 2022). "According to the content of IL-1β, IL-6, IL-8, IL-18, and IL-10, the subgroup of luminal B (HER2-positive) cancer differed from the rest of the luminal subtypes, which suggested that it was HER2 status that was the determining factor influencing on the content of cytokines in saliva." (PMID 36286034, 2022). "Additionally, the use of fucoidan (400 mL/day) has also been used as an anti-inflammatory agent in cancer patients where it demonstrated a reduction in cytokines including IL-6, TNF-a and IL-1β after its oral administration." (PMID 36501043, 2022). "Thus, agents that inhibited the IL-1/IL-1β included IL-1Ra (anakinra), IL-1β antibody (canakinumab), and the inflammasome inhibitor (MCC950) have potential anti-tumor activity in cancers." (PMID 35585567, 2022). "Leptin, interferon‐γ, IL‐1β, IL‐10, adiponectin, and ghrelin did not demonstrate any significant difference between groups when individuals with cancer cachexia were compared against non‐cachectic patients or healthy participants." (PMID 35080147, 2022).
cancer (continued). "In response to ROS produced by cancers, the innate immune system is activated, where macrophages and dendritic cells produce proinflammatory cytokines such as tumor necrosis factor (TNF-α) and Interleukin-1β (IL-1β) to enhance adaptive immunity." (PMID 36503580, 2022). "The addition of 786O cancer cells led to an increase in MMP9, Gro-α, IL-8, IL-6, HB-EGF, and VEGF-A; and the addition of ccRCC PBMCs led to an increase in PDGF-BB and IL-1β as well as a further increase in MMP-9, Gro-α, IL-8, IL-6, and CCL-2 despite cabozantinib treatment." (PMID 34931665, 2021). "In the Canakinumab Anti-inflammatory Thrombosis Outcomes Study (CANTOS), the authors observed, as a prespecified safety analysis, a dose-dependent decrease in overall cancer mortality and in the incidence of non-small-cell lung cancer (NSCLC) in patients treated with an anti-IL-1β antibody." (PMID 33530653, 2021). "Taken together, these results demonstrate that oxidized mtDNA-STING signaling but not TLR9 signaling or IL-1β secretion is involved in the protective antitumor immunity induced by the irradiated cancer cell vaccine." (PMID 32398808, 2021). "The progression of cancer cells could be suppressed by reduced NLRP3 inflammasome and IL-1β expression." (PMID 34747716, 2021). "Moreover, neutrophil expression of thrombospondin 1, IL-1β and the receptor tyrosine-protein kinase MET limit the formation of metastases by blocking the cancer cell mesenchymal-to-epithelial transition and releasing NO individually." (PMID 34674757, 2021). "TAM favors CCL20 production by cancer cells through their secretion of TNF-α, IL-1β and IL-6." (PMID 33924428, 2021). "The crosstalk between cancer cells and fat tissue induces a phenotypic switch, forcing the adipocytes to produce matrix metalloproteases (e.g., MMP11) and pro-inflammatory cytokines such as IL-6, IL1β, and IL-8." (PMID 33026575, 2021). "This may be through EZH2, which is positively influenced by TNFα/IL-1β signaling and has been shown to hypermethylate the ODZ4 promoter in cancer, resulting in repressed miR-708 expression." (PMID 33776573, 2021). "In the current study, CN extracts were not affecting the proliferation and migration of cancer cells but suppressed the pro-inflammatory cytokines such as IL-6, IL-1β, and TNF-α." (PMID 34379689, 2021). "In the worldwide study, the Canakinumab Anti-inflammatory Thrombosis Outcomes Study (CANTOS), over 10,000 patients without cancer were randomized to placebo or a neutralizing antibody to IL-1β for treatment of heart disease." (PMID 33649199, 2021). "Given that the expression of genes such as IL-1β, IL-6, and COX-2 is nuclear factor-κB (NF-κB) dependent, we hypothesize that in poorly invasive cancer cells, the heat is an inhibitor of NF-κB, which acts in a dose-dependent manner." (PMID 34201348, 2021). "As there is evidence suggesting that IL-1α, IL-1β, and IL-1RA are involved in the pathogenesis of HNSCC and can be detected in the saliva of cancer patients, different studies have explored their possible use as diagnostic or prognostic biomarkers for this cancer." (PMID 35048046, 2021). "This association of PTGS2 with inflammatory cytokine expression extends to established cancer; analysis of mRNA-seq data from the Cancer Genome Atlas (TCGA) dataset showed positive correlations of PTGS2 expression with IL1B, IL6, IL8, and CXCL1 in all cancer types." (PMID 33730589, 2021). "On the basis of literature findings on the transactivation of EGFR by IL-1β and the involvement of EGFR in TF expression in other cancer cell types, a Western blot analysis of EGFR phosphorylation at Tyr1068 and Tyr845 in IL-1β-stimulated A549 cells was performed." (PMID 34205482, 2021). "A comparison of serum concentrations of four pro-inflammatory factors (e.g., IL-6, IL-1β, Chemokine (C-X-C Motif) Ligand 8(CXCL8)/IL-8, and TNF-α) in advanced-stage cancer patients showed that IL-1β levels correlated more strongly with clinical characteristics than those of IL-6." (PMID 33557173, 2021).
cancer (continued). "This is of importance as HNSCC cells are able to secrete IL-1β which stimulates other cells of the TME (such as fibroblasts) to generate chemokines and other inflammatory molecules creating an inflammatory TME with cancer promoting properties." (PMID 35048046, 2021). "It has been demonstrated that NET-associated serine proteases such as NE could act as alternative enzymes for processing inflammasome-related IL-1β and IL-18, which subsequently leads to the modulation of PGRN inactivation and MMP-9 activation in cancer." (PMID 34476216, 2021). "While IL1β treatment induced both ROS production and COX-2 expression, FV extract was shown to be inactive, indicating a potential selective role of FV extract on cancer cells." (PMID 33256057, 2020). "Interleukin-1 beta (IL-1β), IL-6, IL-10, transforming growth factor beta (TGF-β), and tumor necrosis factor alpha (TNF-α) are representative cytokines that are important modulators of inflammation and cancer progression." (PMID 33322487, 2020). "IL-8, IL-1β, and matrix metalloproteases (MMP8 and MMP9) released from neutrophils activated endothelial cells, reduced endothelial barrier function, increased transendothelial migration and accelerated the rate of cancer cell extravasation." (PMID 32849639, 2020). "Thereafter, we provide novel mechanistic evidence on the hypoxia-prompted liaison between the HIF-1α/GPER signaling and the IL-1β/IL1R1 axis, toward a metastatic gene expression profile of TNBC cells and the engagement of CAFs in facilitating invasive cancer features." (PMID 32778144, 2020). "Research emphasizes the critical role of humoral factors secreted by cancer cells in the patient’s tissues in the regulation of processes leading to cachexia, which also include pro-inflammatory cytokines IL-6, TNF-α, IFNγ, IL-1α, and IL-1β." (PMID 33158194, 2020). "This was not linked to an intrinsic inability of intestinal ILCs to provide T-cell help, as in vitro IL-1β- and IL-18-stimulated ILCs from non-affected as well as cancer tissue readily upregulated HLA-DR and co-stimulatory molecules." (PMID 32341343, 2020). "After metastasis, pro‐inflammatory cytokines, including Il1α, Il1β, Il6, Il18, and TNF‐α, were significantly induced in lung metastases, indicating that inflammatory cytokines may play a positive role in cancer metastasis." (PMID 34766117, 2020). "Because NLRP1 expression and IL-1β secretion are downstream mediators of TMZ-induced Notch activation, inhibiting NLRP1 and/or IL-1β could be used to regulate cancer aggressiveness and drug resistance, as we have shown in the current study." (PMID 32899791, 2020). "As it has been shown that cannabinoid treatment diminished AKT phosphorylation in different cancer models, we investigated whether CBD decrease of total AKT as well as its activation could be related to the IL-1β EMT progression." (PMID 32244518, 2020). "In addition, the NLRP3 inflammasome has been observed to sustain cancer progression and lymph node metastasis in NSCLC patients by reducing E-cadherin and increasing Snail through IL-1β secretion." (PMID 33014808, 2020). "The inflammatory cytokines interleukin-1 beta (IL-1β) and tumor necrosis factor-alpha (TNF-α) were reported to induce Nurr1 expression, which, in the presence of TGF-β, potentiates SMAD activation of cancer development." (PMID 33086676, 2020). "Cancer inflammatory environment may be established by several factors, including pro-inflammatory cytokines such as TNF-α, IL-1β, and IL-6." (PMID 31252615, 2019). "The balance between IL-1β and IL-18 may be cell-type, tissue, and context dependent, providing a possible explanation for the controversial role of the NLRP3 inflammasome in cancer." (PMID 31558756, 2019). "Since cancer cells of epithelial origin can express IL-1R2, it is possible that in our case cetuximab/EGFR inhibition may be inducing the release of IL-1β as well as IL-1α but we are unable to detect IL-1β due to rapid binding by sIL-1R2." (PMID 30890189, 2019).